FILIP1 (filamin A interacting protein 1)
Description:
By acting through a filamin-A/F-actin axis, it controls the start of neocortical cell migration from the ventricular zone. May be able to induce the degradation of filamin-A.
Synonyms: FILIP; KIAA1275; NMDF
Tractability: Antibody: its Gene Ontology location is reachable by antibodies, with high confidence. PROTAC: ubiquitination databases record sites on it.
Gene: Protein-coding gene on chromosome 6 (75,291,859 to 75,493,800, reverse strand). Ensembl gene ENSG00000118407.
Subcellular location: Cytoplasm, cytoskeleton
Subcellular location (Human Protein Atlas): Actin filaments; Plasma membrane
Pathways (Reactome):
Signal Transduction: RHOD GTPase cycle
Gene Ontology:
Biological process: protein localization to actin cytoskeleton; modification of postsynaptic structure
Cellular component: actin cytoskeleton; cytosol; cytoskeleton; glutamatergic synapse
Genetic constraint (gnomAD): Loss-of-function variants: 60 observed, 104.58 expected, observed/expected ratio (o/e) 0.57, 90% interval 0.47 to 0.71. The upper end of that interval is the gene's LOEUF score, 0.71, which puts it in group 2 of 6, group 1 being the genes least tolerant of losing a copy. Missense variants: 1,314 observed, 1,499.6 expected, observed/expected ratio (o/e) 0.88, 90% interval 0.84 to 0.92. Synonymous variants: 491 observed, 551.35 expected, observed/expected ratio (o/e) 0.89, 90% interval 0.83 to 0.96.
Homologues: Orthologues: chimpanzee FILIP1 (99% identical), macaque FILIP1 (95% identical), pig FILIP1 (95% identical), mouse Filip1 (94% identical), rabbit FILIP1 (92% identical), rat Filip1 (90% identical), dog FILIP1 (85% identical), guinea pig FILIP1 (83% identical), tropical clawed frog filip1 (76% identical), zebrafish filip1b (55% identical), zebrafish filip1a (50% identical), Caenorhabditis elegans C49H3.6 (11% identical). Paralogues in human: FILIP1L (44% identical), LUZP1 (22% identical), CTTNBP2NL (13% identical).
Diseases named in the same sentence as FILIP1 in open-access papers:
FILIP1 is named in the same sentence as 10 diseases in open-access papers, as found by Europe PMC text mining. Sharing a sentence is not in itself a finding about the gene and the disease. The quoted sentences say what the papers report.
arthrogryposis (1 paper, 2023). A rare, non-progressive congenital disorder characterized by multiple joint contractures which are present at birth. "In summary, we provide clinical and genetic evidence that bi-allelic deleterious variants in the FILIP1 gene cause a novel autosomal recessive arthrogryposis phenotype with microcephaly." (PMID 36943452, 2023). "In this study, we describe a novel arthrogryposis phenotype in five patients from three unrelated families characterized by variable severity of multiple congenital joint contractures and associated with homozygous putatively deleterious variants in the FILIP1 gene." (PMID 36943452, 2023).
arthrogryposis multiplex congenita (1 paper, 2023). Arthrogryposis multiplex congenita (AMC) is a group of disorders characterized by congenital limb contractures. "In summary, our data indicate that bi-allelic truncating variants in FILIP1 are causative of a novel autosomal recessive disorder and expand the spectrum of genetic factors causative of arthrogryposis multiplex congenita." (PMID 36943452, 2023).
female infertility (1 paper, 2021). Diminished or absent ability of a female to achieve conception. "Filamin A interacting protein 1 (FILIP1) plays a key role in ovarian dysfunction and female infertility by regulating DNA methylation." (PMID 34093663, 2021).
Intellectual disability (1 paper, 2024). "Deletion of 6q14 has been associated with intellectual disability and several significant micro deformities, and FILIP1 has been suggested to be one of the potential genes in 6q14 that may be related to intellectual disability." (PMID 38736872, 2024).
microcephaly (1 paper, 2023). A congenital or acquired developmental disorder in which the circumference of the head is smaller than normal for the person's age and sex. "The contractural features in combination with microcephaly in our patients strongly support that FILIP1 plays a significant role in both, skeletal muscle cell differentiation and brain development, during embryonic development." (PMID 36943452, 2023).
tumor (4 papers, 2020 to 2025). "LUZP1 shows homology to FILIP1 (Filamin A Interacting Protein 1), a protein interactor of filamin and actin, and FILIP1L (FILIP1 Like), a suppressor of tumor cell migration." (PMID 33869174, 2021).
infection (1 paper, 2025). The state of being infected such as from the introduction of a foreign agent such as serum, vaccine, antigenic substance or organism. "Additionally, genes related to cell adhesion such as ADGRF5, CAVIN2, FAT3, FILIP1, GSN, and TSPAN11 were downregulated in both the variants at 24hpi whereas CAV1, CAVIN1, GPC3, POSTN, SUSD2, and TSPAN7 were downregulated only after Delta variant infection at 24 hpi." (PMID 41200555, 2025).
FILIP1 also shares sentences with these, for which no sentence is quoted: asthma (1 paper); osteoarthritis (1); Sepsis (1).